LEP (leptin)
Diseases named in the same sentence as LEP in open-access papers (continued):
Sharing a sentence is not in itself a finding about the gene and the disease.
Obesity (continued). "The association of the FTO gene with obesity was first identified in the Caucasian population, and the FTO gene’s SNPs have been shown to be associated with obesity-related parameters such as leptin levels, subcutaneous fat, fat mass, and waist and hip circumference." (PMID 31810473, 2019). "Moreover, while a defect in leptin signaling is associated with hyperphagia and a marked decrease in energy expenditure in mice, it mainly increases appetite in humans, resulting in obesity." (PMID 31547031, 2019). "So leptin deficiency or leptin resistance promote diabetes, obesity, and other metabolic disorders." (PMID 31093312, 2019). "High levels of leptin, usually associated with obesity, are risk factor for bone loss." (PMID 30758470, 2019). "Collectively, these data suggest that hypothalamic inflammation may contribute to obesity-associated leptin resistance in the brain." (PMID 31739649, 2019). "Therefore, leptin has, so far, been of limited clinical use, although the marked obesity caused by leptin deficiency clearly proves the biological importance of leptin." (PMID 30888399, 2019). "Accordingly, although circulating GIP levels are increased in both DIO and Lepob/ob mice, the underlying mechanisms differ, and the anti-obesity actions of α-GIs and leptin sensitizers may be mediated partly by the suppression of GIP secretion." (PMID 31509948, 2019). "In agreement with our results, it has been recently reported that treatments like proanthocyanidins, which reduce obesity-induced hypothalamic inflammation and leptin resistance, are associated with decreased caloric intake and increased gene expression of POMC in the hypothalamus." (PMID 30642033, 2019). "Obesity-associated inflammation has been proposed to play an important role underlying the differences in iron profiles between Ob and AW groups, perhaps through the induction of hepcidin production by cytokines such as IL-6 and leptin." (PMID 30909605, 2019). "Plasma levels of leptin positively correlate with the amount of body fat and BMI, increase with age, and contribute to the inflammatory status of the AT associated with obesity." (PMID 30814978, 2019). "Therefore, deficiency of leptin or the leptin receptor leads an impaired energy expenditure and increased food intake, and thus to obesity." (PMID 31032262, 2019). "Despite emerging evidences support leptin as a mediator of obesity-associated CRC4, the mechanisms underlying this pathobiology remain unclear." (PMID 31506433, 2019). "Mutations of MC4R are known to cause a monogenic form of obesity in humans via leptin." (PMID 31852448, 2019). "Likewise, although leptin-deficient monogenic mutant rodents show obesity and diabetes immediately after ablation, human T2DM is most prevalent in the middle aged and elderly." (PMID 31805752, 2019). "Overwhelming evidence indicates that hyperleptinemia and leptin resistance have a central pathogenic role in the blunted anorexigenic effect and suppressed energy expenditure, as well as in the systemic proinflammatory state observed in obesity and in the MS." (PMID 31404407, 2019). "Mammary tumorigenesis is severely linked to obesity, one potential connection is leptin." (PMID 31671408, 2019). "In addition, leptin-deficient (ob/ob) mice became insulin-resistant due to deficiency of leptin, and developed severe obesity." (PMID 32009986, 2019). "Furthermore, it has been described that leptin enhances the inductive action of IL-1 and IL-8 on iNOS, and thus on NO production, contributing to an increased risk of osteoarthritis in obesity." (PMID 31500090, 2019). "In addition, studies showed that obesity-induced leptin and insulin resistance are associated with impaired hypothalamic regulation of energy homeostasis." (PMID 31052312, 2019).
Obesity (continued). "In this context, the knowledge of the complex molecular network of leptin signaling responsible for mammary carcinogenesis may provide novel ideas for the prevention and treatment of breast cancer associated to obesity." (PMID 31380268, 2019). "The reduced production of H2S during sustained obesity might contribute to the loss of the leptin-induced, EDH-mediated responses observed in rats with long-term obesity." (PMID 31370156, 2019). "However, only a few genes are linked with the development of the monogenic form of obesity and these genes include, among others, leptin, leptin receptor, proopiomelanocortin, and prohormone convertase I." (PMID 31557979, 2019). "Dysconnectivity between the putamen and PG in obesity could be associated through the mechanism for leptin regulation." (PMID 30881281, 2019). "In addition, our results suggest that a genetic deletion favoring obesity and hyperinsulinemia (leptin-deficiency) accelerates steatohepatitis and fibrosis progression." (PMID 31023717, 2019). "Furthermore, clinical reports unequivocally link elevated serum leptin levels (caused by obesity) to an increased risk of certain cancers including prostate, breast, colorectal, renal cancers and multiple myeloma." (PMID 30659329, 2019). "Moreover, many studies have demonstrated the association of the LEP gene mutations and obesity in obese patients." (PMID 31871931, 2019). "Interestingly, numerous studies clearly reported that chronic exposure to high leptin levels, which mimics obesity-associated hyperleptinemia, promotes hypothalamic insulin resistance through the impairment of neuronal insulin signaling." (PMID 30906281, 2019). "We hypothesize that cord blood epigenetic changes will be associated with measures of neonatal adiposity such as percent body fat, fat mass, and cord blood leptin, and provide insight into early life mechanisms of future obesity risk." (PMID 31851703, 2019). "High levels of leptin increase oxidative stress in endothelial cells, favor vascular smooth muscle cell migration and proliferation, reduce arterial distensibility, and contribute to obesity-associated hypertension." (PMID 31500090, 2019). "Insulin, insulin-like growth factor-1 (IGF1), leptin, adiponectin, steroid hormones, and cytokines are some host factors associated with obesity that not only influences the initiation and progression of breast cancer, but also affects its response to therapies." (PMID 31121868, 2019). "Leptin deficiency leads to constant hunger, which leads to hyperphagia and obesity." (PMID 33499919, 2019). "Leptin hormone is secreted from white adipose tissue and supposed to bind to its receptors in the hypothalamus in the brain to stop eating and regulate body fats in addition to insulin sensitivity; so leptin polymorphisms is a key factor linking obesity and type 2 diabetes." (PMID 32042833, 2019). "Administration of leptin completely recovers the obesity phenotype of ob/ob mice and induces anorexia and body weight loss in normal mice, suggesting that leptin negatively regulates feeding behaviors and inhibits obesity." (PMID 31447640, 2019). "The mechanism that may explain the association between MS pathogenesis and obesity is the presence of significantly increased levels of the adipose tissue hormone leptin in both patient populations." (PMID 29525910, 2018). "However, in another study, very high levels of plasma leptin were associated with obesity hypoventilation." (PMID 29675134, 2018). "Obesity is associated with leptin resistance, where high plasma leptin concentration was observed in most obese humans and rodents but this hyperleptinemia may not reduce appetite or increase energy expenditure." (PMID 29713567, 2018). "Leptin inhibits appetite by acting on the satiety center in the hypothalamus, which activates the sympathetic nervous system causing the body to burn fat and control obesity." (PMID 30086171, 2018).
Obesity (continued). "That is to say that high leptin levels may be one of the main mechanisms underlying the low testosterone level caused by the concomitant exposure of mice to obesity and DEHP." (PMID 29887939, 2018). "It has been well established that obesity could cause ER stress, and hypothalamic ER stress leads to leptin/insulin resistance and hyperphagia." (PMID 30555354, 2018). "Importantly, PTP1B-deficient mice display the resistance to diet-induced obesity, augmented energy expenditure, hypersensitivity to leptin, and enhanced phosphorylation levels of JAK2 and STAT3 in the hypothalamus." (PMID 30383868, 2018). "Additionally, genetic factors such as mutation in the leptin pathway leads to monogenic obesity while chromosomal abnormalities results in syndromic obesity." (PMID 30567565, 2018). "Therefore, obesity is associated with excessive plasma leptin concentration (hyperleptinemia) as a result of leptin resistance, and plasma leptin concentrations are generally proportional to the degree of adiposity." (PMID 30373146, 2018). "However, obesity-associated hyperleptinemia is linked to decreased leptin sensitivity, at least in adults." (PMID 29706935, 2018). "However, physical exercise has minimal effects on obesity in animals with leptin signaling deficiency." (PMID 29896090, 2018). "Clinical studies demonstrate an impact of obesity on the risk of infertility, and it is also established that obesity may lead to deregulation in leptin function that results in maternal disease." (PMID 29160594, 2018). "Teasing apart the relative contribution of physical, weight-dependent mechanisms from physiological-dependent mechanisms is inherently difficult due to the close relationship between obesity and its associated changes in glycemic control, insulin action, and leptin signaling." (PMID 30127766, 2018). "Obesity, characterized by high levels of leptin, is a PC risk factor." (PMID 30004402, 2018). "Obesity is associated with an increased level of leptin prevailing in the expanding WAT." (PMID 30333759, 2018). "Hence, obesity promotes hyperleptinemia, which, in turn, self-promotes leptin resistance and further promotes obesity, making leptin resistance both a consequence and cause of obesity." (PMID 30583468, 2018). "Obesity can be associated with leptin resistance; however, we previously demonstrated that in female rats overweight due to neonatal overnutrition hypothalamic sensitivity to leptin is accentuated during the peripubertal period." (PMID 29706935, 2018). "Indeed, in vitro studies have reported a role for leptin in disc degeneration, and leptin is proposed as a causative link between obesity and osteoarthritis." (PMID 29483883, 2018). "In addition, we evaluated the possible mechanisms (high leptin level and oxidative stress in testicular tissue) underlying the joint-damaging effect of obesity and DEHP upon the male reproductive system." (PMID 29887939, 2018). "We have yet to determine the possible obesity-associated alterations in leptin signaling in the SAA3−/− mice and how this may impact lymphocyte proliferation and activity." (PMID 30410021, 2018). "Thus, obesity-associated factors including leptin and resistin are crucial for cancer cell growth as well as for outcome of therapeutic response." (PMID 29568521, 2018). "Although being rather contradictory, the existing data demonstrate that the metabolic effects of Zn in obesity may be associated with its interference with leptin production." (PMID 28965330, 2018). "Moreover, leptin-deficient ob/ob mice and leptin receptor-deficient db/db mice were important for their wide use in obesity-induced T2DM, although leptin or leptin receptor disorder is not a key point in human T2DM (Wang, Chandrasekera & Pippin, 2014)." (PMID 29682407, 2018). "Considering leptin as a serious pro-inflammatory modulator, its effects might explain the association between obesity and MS, since leptin is also increased in MS patients." (PMID 29525910, 2018).
Obesity (continued). "These associations remained statistically significant after adjustment for BMI, suggesting that these leptin variants may be associated with colorectal carcinogenesis independently of obesity." (PMID 30379922, 2018). "Obesity is associated with elevated circulating leptin levels and hypothalamic leptin resistance." (PMID 30424579, 2018). "Furthermore, obesity is associated with increased levels of circulating leptin, a key regulator of body weight and metabolism with known prothrombotic actions." (PMID 29910857, 2018). "Moreover, knockout mouse studies have shown that disrupting neural STAT3 causes leptin-resistant conditions such as obesity, diabetes, and thermal dysregulation." (PMID 29596388, 2018). "Should hyperleptinemia eventually emerge as the main driving force of obesity-associated male hypogonadism, then future leptin sensitizers (currently being developed) might solve the obesity-induced testicular malfunction before weight loss occurs." (PMID 29998109, 2018). "This in turn causes leptin resistance culminating in obesity." (PMID 29487844, 2018). "Both an early growth restriction and perturbed hypothalamic leptin sensing suggest that adult Nnat+/−p mice may be susceptible to obesity in later life." (PMID 30279096, 2018). "However, melatonin’s effects against the mechanisms involved in the leptin-induced carcinogenesis supports its use in reducing the BC risk associated with obesity." (PMID 29415446, 2018). "Low levels of leptin are correlated with a higher risk of obesity in humans too." (PMID 30201891, 2018). "Leptin levels in adulthood are associated inversely to birth weight and are related to obesity." (PMID 30103773, 2018). "However, leptin is unable to exert its effect during diet-induced obesity, and several molecular alterations have been associated with attenuated leptin/STAT3 signaling." (PMID 30441779, 2018). "This review summarizes the latest data regarding the role of leptin as a mediator of innate and adaptive immune cells activity, and its effects on obesity-associated metabolic disorders, namely T2DM and NAFLD, and autoimmune and/or inflammatory rheumatic diseases, such as OA and RA." (PMID 29910742, 2018). "In obesity, hypothalamic leptin sensitivity is reduced causing failure to adequately suppress food intake and increase energy expenditure (i.e. leptin sensing circuitry is insensitive to a pharmacological dose of leptin; termed leptin resistance)." (PMID 29311632, 2018). "Obesity is associated with chronically increased plasma leptin concentrations." (PMID 29560551, 2018). "In addition, higher levels of leptin, an adipokine related to obesity, has also been associated with increased risk of psoriasis." (PMID 29680995, 2018). "Thus, it is plausible that participants with higher leptin experienced a reduced risk of cancer mortality due to lower risk of obesity or less active adipose tissue for a given body-mass index (since we adjusted for this in our analysis)." (PMID 29662629, 2018). "Leptin is a natural component of breast milk, and is considered an essential nutrient during lactation in protecting against the development of obesity and associated pathologies in adulthood." (PMID 29618984, 2018). "Specifically, the IEPalm with a higher concentration of C16:0 located at the sn-2 position of the TAG backbone tended to raise serum TAG, contributing to body weight gain, an increase in body fat percentage, a rise in circulating leptin, and hence, an increased risk of obesity." (PMID 30126103, 2018). "It demonstrated that with obesity, there is an increased risk of leptin and insulin resistance." (PMID 30405010, 2018). "In human studies, leptin levels are positively correlated with obesity in the general population and positively associated with sedentary behavior, even after adjusting for various possible confounding factors including demographics, medications, and body mass index (BMI)." (PMID 29949600, 2018).
Obesity (continued). "However, it is not well understood how obesity-associated elevation of leptin increases the risk of asthma." (PMID 29891850, 2018). "The establishment of LepR-deficient macrophage cell line DB-1, derived from differentiated bone marrow cells of Lepr-knockout mice, provide a powerful tool to study the role of leptin and its receptor in obesity-associated inflammation and immune system deregulation." (PMID 29910742, 2018). "On the other hand, CR may impact the obesity-cancer pathway, by reducing serum insulin, leptin, and associated inflammation by limiting NFκβ—related gene expression." (PMID 30202241, 2018). "Bone marrow was harvested and differentiated into macrophages to determine whether there were differences in macrophage cholesterol efflux capacity due to the genetic deficiency of leptin or the induction of obesity." (PMID 30216355, 2018). "A maternal high-fat diet exacerbated obesity in the high-fat-fed daughters, causing them to weigh more, have more fat, and have higher serum levels of leptin as adults, accompanied by dozens of gene expression changes and thousands of DNA methylation changes in their livers and hearts." (PMID 29447215, 2018). "Many studies have shown that leptin, an adipokine highly elevated in the obese population, represents a paramount role on affecting lung physiology and mechanics and thus, regulating respiratory function, which is correlated with obesity-associated asthma." (PMID 29891850, 2018). "Interestingly, we found that DNAJC27 had a positive association with leptin, which is one of the major adipokines strongly associated with obesity." (PMID 30131766, 2018). "Likewise, obesity associated increases in circulating insulin, leptin, and adiponectin were ameliorated to a similar extent by hypoxia and by restricted feeding." (PMID 30210452, 2018). "In conclusion, our data show that DNAJC27 is elevated in obese and T2D individuals and was positively associated with obesity biomarkers such as leptin and resistin suggesting that this protein may play a role in the pathophysiology of these disorders." (PMID 30131766, 2018). "Leptin deficiency was the first cause of monogenic obesity to be demonstrated in a human patient." (PMID 29880780, 2018). "Thus, leptin action deficits in the hypothalamus alone are sufficient to cause obesity, highlighting the importance of hypothalamus neurons in the etiology of obesity." (PMID 30185666, 2018). "Leptin affects food consumption and energy expenditure acting directly on the hypothalamus (a brain region involved in energy homeostasis) and hyperleptinemia has been associated to obesity and the related disorders." (PMID 29599711, 2018). "While the two peptides could inhibit food intake as well as leptin secretion, they may alleviate leptin resistance, which is commonly associated with obesity." (PMID 30087623, 2018). "Obesity is a risk factor for PC that could affect 5-FU effectiveness through the adipokine leptin, which is a known proliferation, survival factor and Notch inducer." (PMID 29719602, 2018). "In parallel, leptin resistance is one of the important pathogenic factors of obesity and OSA." (PMID 29675134, 2018). "The possible differing relationship of Dialister with leptin and oxytocin could be explained at least in part by opposite association of these hormones with obesity and T2D reported in previous studies." (PMID 29596446, 2018). "But the administration of chemical chaperons such as 4-phenylbutyric acid (4-PBA) and tauroursodeoxycholic acid (TUDCA) has reduced the ER stress in diet-induced obesity and increased the leptin sensitivity by ten-folds beside to weight loss during high-fat diet." (PMID 29868503, 2018). "Similarly while there are some monogenic causes of obesity, generally involving the hormone leptin and its receptor, these are rare: being present in fewer than 5% of patients with severe obesity." (PMID 30371347, 2018).